MOCS2 (molybdenum cofactor synthesis 2)
Description:
Acts as a sulfur carrier required for molybdopterin biosynthesis. Component of the molybdopterin synthase complex that catalyzes the conversion of precursor Z into molybdopterin by mediating the incorporation of 2 sulfur atoms into precursor Z to generate a dithiolene group. In the complex, serves as sulfur donor by being thiocarboxylated (-COSH) at its C-terminus by MOCS3. After interaction with MOCS2B, the sulfur is then transferred to precursor Z to form molybdopterin. Catalytic subunit of the molybdopterin synthase complex, a complex that catalyzes the conversion of precursor Z into molybdopterin. Acts by mediating the incorporation of 2 sulfur atoms from thiocarboxylated MOCS2A into precursor Z to generate a dithiolene group (By similarity). Together with MBIP, inhibits the activity of stress kinase EIF2AK2/PKR; this may suppress JNK activation and subsequent stress-responsive transcription, or suppress eIF2a phosphorylation to favor translation.
Synonyms: MOCS2B; MCBPE; MOCO1; MOCS2A; MOCODB; MOCODB1; MPTS
Tractability: PROTAC: ubiquitination databases record sites on it.
Gene: Protein-coding gene on chromosome 5 (53,095,679 to 53,113,016, reverse strand). Ensembl gene ENSG00000164172.
Subcellular location: Cytoplasm, cytosol; Nucleus
Subcellular location (Human Protein Atlas): Cytosol; Nuclear speckles; Nucleoplasm
Pathways (Reactome):
Metabolism: Molybdenum cofactor biosynthesis
Gene Ontology:
Molecular function: molybdopterin synthase activity; protein binding
Biological process: Mo-molybdopterin cofactor biosynthetic process; molybdopterin cofactor biosynthetic process
Cellular component: cytosol; molybdopterin synthase complex; nucleus
Genetic constraint (gnomAD): Loss-of-function variants: 11 observed, 17.08 expected, observed/expected ratio (o/e) 0.64, 90% interval 0.4 to 1.07. The upper end of that interval is the gene's LOEUF score, 1.07, which puts it in group 4 of 6, group 1 being the genes least tolerant of losing a copy. Missense variants: 171 observed, 186.57 expected, observed/expected ratio (o/e) 0.92, 90% interval 0.81 to 1.04. Synonymous variants: 74 observed, 70.96 expected, observed/expected ratio (o/e) 1.04, 90% interval 0.86 to 1.26.
Gene-disease validity (ClinGen):
ClinGen rates the evidence that MOCS2 causes each of these diseases.
sulfite oxidase deficiency due to molybdenum cofactor deficiency type B1 (autosomal recessive): Definitive.
Homologues: Orthologues: chimpanzee MOCS2 (99% identical), macaque MOCS2 (95% identical), rabbit MOCS2 (90% identical), rat Mocs2 (84% identical), mouse Mocs2 (82% identical), guinea pig MOCS2 (80% identical), pig MOCS2 (77% identical), rabbit MOCS2 (72% identical), zebrafish mocs2 (51% identical), tropical clawed frog MOCS2 (47% identical), Drosophila melanogaster Mocs2B (43% identical), Caenorhabditis elegans nmrk-1 (37% identical). Paralogues in human: MBIP (20% identical), NMRK2 (11% identical), NMRK1 (9% identical).
Diseases named in the same sentence as MOCS2 in open-access papers:
MOCS2 is named in the same sentence as 18 diseases in open-access papers, as found by Europe PMC text mining. Sharing a sentence is not in itself a finding about the gene and the disease. The quoted sentences say what the papers report.
molybdenum cofactor deficiency (6 papers, 2016 to 2026). "The second individual had a homozygous class IV missense variant in MOCS2 (c.226G > A, p.(Gly76Arg)) which is associated with Molybdenum cofactor deficiency." (PMID 39400946, 2025). "Xanthinuria type III is caused by molybdenum cofactor deficiency (MoCD) due to pathogenic variants in MOCS1, MOCS2, MOCS3, or GEPH genes." (PMID 40707723, 2025). "Molybdenum cofactor deficiency (MoCD) is a rare and severe autosomal recessive in-born error of metabolism caused by the mutation in MOCS1, MOCS2, MOCS3 or GEPH genes, with an incidence ranging between 1 in 100,000 and 200,000 live births." (PMID 37371303, 2023).
xanthinuria (2 papers, 2024 to 2025). A metabolic metabolic disorder characterized by excess urinary excretion of the purine base xanthine. "In conclusion, we discovered a novel MOCS2 variant, prevalent in the Roma population, that is associated with xanthinuria and mild clinical phenotypes." (PMID 40707723, 2025). "Hypouricemia should be considered in the differential diagnostic algorithm of pediatric and adult patients with neurological symptoms, and MOCS2 should be considered in gene panels for xanthinuria screening." (PMID 40707723, 2025). "Genetic causes of xanthinuria with NL and/or NC consist of Xanthinuria (XDH and MOCOS genes) and Molybdenum cofactor deficiency (MOCS1 and MOCS2 genes)." (PMID 38606357, 2024).
Acute encephalopathy (1 paper, 2026). "METHODS: Clinical and genetic information were collected from two patients showing acute encephalopathy, each harboring mutated molybdenum cofactor synthesis gene 2 (MOCS2)." (PMID 41731370, 2026).
atopic asthma (1 paper, 2023). An asthma that is characterized by symptoms that are triggered by an allergic reaction caused by inhaled allergens such as dust mite allergen, pet dander, pollen and mold. "Notably, MSL1, MOCS2, NUPR1, and SGF29 interact with proteins encoded by three genes that are associated with post bronchodilator FEV1, atopic asthma and AD." (PMID 36574990, 2023).
lung adenocarcinoma (1 paper, 2010). A carcinoma that arises from the lung and is characterized by the presence of malignant glandular epithelial cells. "We performed high-resolution array comparative genomic hybridization analysis of lung adenocarcinoma in sixty never smokers and identified fourteen new minimal common regions (MCR) of gain or loss, of which five contained a single gene (MOCS2, NSUN3, KHDRBS2, SNTG1 and ST18)." (PMID 21151896, 2010).
Molybdenum cofactor deficiency type B (1 paper, 2026). "BACKGROUND: Molybdenum cofactor deficiency type B (MoCD-B) is a rare autosomal recessive metabolic disorder caused by mutations in MOCS2." (PMID 41731370, 2026).
neurodegenerative disease (1 paper, 2022). A disorder of the central nervous system characterized by gradual and progressive loss of neural tissue and neurologic function. "This review provides an overview of the roles of MoaE and MOCS2 in normal cellular processes and neurodegenerative disease, as well as directions for future research." (PMID 35744859, 2022).
MOCS2 also shares sentences with these, for which no sentence is quoted: epilepsy (2 papers); metabolic disorder (2); biotinidase deficiency (1); developmental delay (1); diabetes (1); Encephalopathy (1); Glucose intolerance (1); hereditary xanthinuria (1); microcephaly (1); nonketotic hyperglycinemia (1); oral cancer (1).